ALK (ALK receptor tyrosine kinase)
Diseases named in the same sentence as ALK in open-access papers (continued):
Sharing a sentence is not in itself a finding about the gene and the disease.
metastatic disease (71 papers, 2012 to 2026). "Positive EGFR mutations, KRAS mutations, and EML4::ALK fusion in metastatic tumors often suggest a lung origin." (PMID 39980562, 2025). "The primary and metastatic tumors shared ALK rearrangement and other mutations support they were derived from a single clone origin." (PMID 37637057, 2023). "While ALK was wild-type in the metastatic tumor at diagnosis, an F1174L mutation occurred at low allelic fractions in the second biopsy which was derived from the primary tumor." (PMID 36807339, 2023). "EML4‐ALK V3 in NSCLC is associated with a relatively poor response to ALK inhibitors and more aggressive metastatic disease than longer EML4‐ALK variants such as V1." (PMID 34661367, 2021). "In the future, more attention should be paid to EGFR mutations and ALK rearrangements in primary and metastatic tumors to allow for accurate diagnosis and personalized, precise medication in clinical practice." (PMID 33285759, 2020). "We therefore investigated ALK protein expression and underlying genetic aberrations in a cohort of patients who received chemotherapy in the setting of metastatic disease, focusing on clinical and prognostic implications." (PMID 25083769, 2014). "Furthermore, within the ALK-positive cohorts, 6 (42.9%) of 14 patients had stage IV disease, but only 10 (10.2%) of 98 patients with EGFR mutations had metastatic disease, which suggests a trend toward higher clinical stage among ALK-positive patients compared with EGFR mutant cohorts (P = 0.002)." (PMID 34234236, 2021). "Firstly, despite our focus on patients with oligo-residual NSCLC and EGFR/ALK wildtype, there remains inherent heterogeneity, such as driver gene alteration status, histology, overall disease burden, metastatic disease interval, and previous systemic therapy." (PMID 41213939, 2025). "Clinically, the three reported index patients with ALK-rearranged LCNEC presented with an aggressive course of metastatic disease and multiple brain metastases." (PMID 35756632, 2022). "All of the primary and metastatic tumors in both cases showed positive anaplastic lymphoma kinase (ALK) immunostaining and ALK rearrangement via fluorescence in situ hybridization." (PMID 35280868, 2022). "Previously, three cases (cases 2-159, 5-177, and 6-184) reportedly showed ALK-positive staining in metastatic tumors." (PMID 34090412, 2021). "Recent long-term follow-up results from 110 ALK-positive patients who received the ALK inhibitor crizotinib, showed a median OS of 6.8 years in patients with metastatic disease." (PMID 32560187, 2020). "Based on the high concordance of ALK status between the primary and metastatic tumors, we presumed ALK rearrangement in 11/16 (68.8%) cases in the present study." (PMID 31455365, 2019). "The diagnosis of ALK fusions in NSCLC has led to the development of potent and selective ALK inhibitors that have dramatically changed the treatment landscape for patients who present with late stage metastatic disease." (PMID 30038711, 2018). "Although the incidence of ALK-positive NCSLC only accounts for 5% of all NCSLC cases, the efficacy of tyrosine kinase inhibitors with ALK activity ensures that these agents will have a place in the treatment of advanced and metastatic disease." (PMID 30564472, 2018).
metastatic disease (continued). "The metastatic tumor harbored a PHOX2B deletion and a missense mutation of NRAS (p.Gln61Lys), whereas an ALK mutation (p.Phe1174Leu) was detected only in the primary tumor." (PMID 28915622, 2017). "Firstly, fine needle biopsy or aspiration of primary and/or metastatic tumours and pleural effusions are feasible for the detection of ALK gene translocations." (PMID 28887531, 2017). "Immunostaining showed intratumor heterogeneity of ALK rearrangement in primary carcinomas and 50% (3/6) of metastatic tumors with ALK-negative staining." (PMID 23341890, 2013). "Next, we performed ALK immunohistochemistry staining (ALK-IHC) of primary and metastatic tumors of all ALK-positive cases." (PMID 23341890, 2013). "Eligible patients were characterized by metastatic non-squamous NSCLC without sensitizing EGFR or ALK mutations, and had not been previously treated for metastatic disease." (PMID 38241591, 2024). "During these years, only 2281 person-years of EGFR- and ALK-targeted therapies were dispensed to Medicaid patients, suggesting that an estimated 66% of Medicaid patients with EGFR- and ALK-altered metastatic disease received indicated targeted therapies across all states." (PMID 36696113, 2023). "The patient exhibited a rapid disease response to ALK tyrosine kinase inhibitors alectinib with a complete remission of widespread metastatic disease and progression-free survival of more than 26 months, but not to darafenib plus trametinib targeted BRAF V600E therapy." (PMID 36221356, 2022). "The therapeutic strategy that targets this oncogenic fusion has greatly improved the prognosis of patients with advanced and metastatic disease, evidenced by an unprecedented 5-year survival rate of approximately 50% in ALK-positive NSCLC patients treated with an ALK inhibitor." (PMID 33761908, 2021). "Recently, the third-generation ALK inhibitor lorlatinib has been received an accelerated approval by the U.S. FDA for patients with ALK-positive NSCLC whose metastatic disease were ineffective in response to targeted therapies such as crizotinib, ceritinib, alectinib, and brigatinib." (PMID 35004700, 2021). "Patients with advanced or metastatic disease receive a cisplatin-based combination therapy if they carry neither an epithelial growth factor receptor (EGFR) nor an anaplastic lymphoma kinase (ALK) mutation." (PMID 29518977, 2018). "Furthermore, there were only 3 cases (Cases 2, 5 and 6) with ALK-positive staining in the metastatic tumors." (PMID 23341890, 2013). "Finally, ALK immunofluorescence staining (ALK-IF) was also employed in ALK-IHC of the primary and metastatic tumors in all ALK-positive cases, which further confirmed the ALK-IHC findings." (PMID 23341890, 2013). "ESMO guidelines do not recommend local treatments with radical intent for EGFR-mutated and ALK-rearranged metastatic disease if it is not in the oligoprogressive scenario (see paragraph below), though the level of evidence is low due to the lack of randomised data." (PMID 39996875, 2025). "Notably, pleural metastatic tumors weakly express ALK (clone D5F3), but 75% were positive for ALK rearrangement by FISH; therefore, the results of immunohistochemical and FISH may be inconsistent for distant metastases." (PMID 31455365, 2019). "Therefore, ALK-targeted TKIs can be used to treat metastatic disease." (PMID 29312572, 2017). "Therefore, primary tumours can clearly represent the ALK status of the metastatic tumours." (PMID 28887531, 2017). "The tumor in the right greater psoas muscle was identified as a metastatic tumor from the lung tumor based on ALK-positivity and the EML4-ALK fusion." (PMID 37920641, 2023). "In GEMSTONE-302 [NCT03789604], eligible patients had histologically or cytologically confirmed stage IV squamous or non-squamous NSCLC without known EGFR sensitizing mutations, ALK, ROS1, or RET fusions, no previous systemic treatment for metastatic disease." (PMID 38241591, 2024).
metastatic disease (continued). "Although most of the ALK-RCC patients present with an indolent behavior, they may be characterized by metastatic disease and death, as documented in about 25% of reported cases." (PMID 35409355, 2022). "For patients with metastatic disease, the outcome largely depends on the identification of a targetable driver such as EGFR, ALK, ROS1, ERBB2, BRAF, MET and more recently KRAS, RET, NRG1 and NTRK1-2-3, as mutations or gene fusions are highly predictive of response to matched targeted therapy." (PMID 35326552, 2022). "A recent phase 3 clinical trial compared lorlatinib with first generation ALK inhibitor crizotinib in 296 patients with advanced ALK-positive NSCLC who had received no previous systemic treatment for metastatic disease." (PMID 35096602, 2021). "For 33 patients who were ALK negative in the primary tumors, 1 (3%) was ALK positive in their metastatic tumors." (PMID 29312572, 2017). "Although the tumor was negative for ALK, the follow-up did not indicate metastatic disease or recurrence." (PMID 25945274, 2015). "For Case 4, even though the metastatic tumors comprised most of the adenocarcinoma component, ALK immunostaining was still completely negative." (PMID 23341890, 2013). "Even more surprisingly, we found that 50% of the metastatic tumors were completely negative for ALK immunostaining (IHC and IF)." (PMID 23341890, 2013). "Although the tumour was negative for ALK, a 12-month followup did not indicate metastatic disease or recurrence." (PMID 23091756, 2012). "Furthermore, the presence of p-ALK correlated with an absence of metastatic disease at the time of diagnosis (P = 0.012)." (PMID 34029351, 2021). "Cancer therapy including ALK inhibitors may change the TIME in primary and metastatic tumors." (PMID 33352665, 2020). "In addition, as the third generation ALK inhibitor, Lorlatinib has also been approved for the treatment of metastatic NSCLC patients with ALK fusion, on condition that the disease has progressed on Crizotinib or at least one other ALK inhibitor such as Alectinib or Ceritinib for metastatic disease." (PMID 32457845, 2020). "Although there are limited data in the literature, there has not yet been any reported recurrence or death in patients with an ALK-rearranged Spitz tumor, and the available sentinel lymph node biopsy (SLN) data have never demonstrated metastatic disease." (PMID 38390852, 2024). "Consistent with the ALK staining, p-JAK2 was present only in the metastasis of these three cases, and p-STAT6 staining did not appear in any metastatic tumors." (PMID 34090412, 2021).
angioimmunoblastic T-cell lymphoma (70 papers, 2006 to 2026). A mature T-cell non-Hodgkin lymphoma, characterized by systemic disease and a polymorphous infiltrate involving lymph nodes and extranodal sites. "The most common subtype is PTCL-NOS; 26%, followed by angioimmunoblastic T-cell lymphoma (19%), ALCL with anaplastic lymphoma kinase (ALK)-positive (7%) and ALK-negative (6%) forms, and enteropathy-associated T-cell lymphoma (<5%)." (PMID 41561549, 2025). "PTCL-NOS, angioimmunoblastic T-cell lymphoma (AITL), ALK-negative (ALK−) ALCL, and NK-TCL, the most common subtypes of PTCL, are each associated with <35% 5-year overall survival." (PMID 29789628, 2018). "Primary nodal PTCL is the most frequent subtype and includes PTCL not otherwise specified (PTCL-NOS), angioimmunoblastic T-cell lymphoma (AITL), and anaplastic lymphoma kinase positive (ALK+) and negative (ALK−) anaplastic large-cell lymphoma (ALCL)." (PMID 37685372, 2023). "At present, many physicians adopt autoSCT as upfront consolidation in patients achieving a CR or partial remission (PR) in the following subtypes: PTCL—not otherwise specified (PTCL-NOS), angioimmunoblastic T-cell lymphoma (AITL) and ALCL, ALK-negative." (PMID 33114606, 2020). "We aimed to retrieve novel information on the role of histology, disease status prior to transplantation, and donor choice for patients with PTCL not otherwise specified (NOS), angioimmunoblastic T-cell lymphoma (AITL), and anaplastic lymphoma kinase (ALK)-negative ALCL." (PMID 41723532, 2026). "Primary diseases included NK/TCL (n = 20), PTCL (not otherwise specified, PTCL-NOS) (n = 10), ALK negative anaplastic cell lymphoma (ALK-ALCL) (n = 10), angioimmunoblastic T-cell lymphoma (AITL) (n = 9) and cutaneous T-cell lymphoma (CTCL) (n = 3)." (PMID 35999255, 2022). "Nodal PTCL is the common subtype of PTCL, including PTCL not otherwise specified (PTCL-NOS, 25%), angioimmunoblastic T-cell lymphoma (AITL, 18%), anaplastic large-cell lymphoma (ALCL), and both ALK positive (6%) and ALK negative (5%)." (PMID 32185229, 2020).
thyroid cancer (63 papers, 2011 to 2026). "Unlike the diverse ALK fusion variants seen in other cancers, thyroid cancer cells specifically exhibit STRN-ALK fusions, which encode for striatin." (PMID 40363930, 2025). "The pathological diagnosis was thyroid IMT; however, strong expression of thyroid epithelial markers and the ALK mutation suggested possible thyroid carcinoma components or malignant potential." (PMID 40636700, 2025). "In contrast to different ALK translocation fusions, identified in other tumor types, the STRN-ALK fusions encoding for striatin were identified in thyroid cancer cells." (PMID 29455653, 2018). "The COSMIC database reports ALK sequencing results for 720 thyroid cancer samples, identifying 12 samples with mutations, including ALK-L1198F and ALK-G1201E." (PMID 28030793, 2017). "Based on our findings, the involvement of ALK activating mutations in the context of the full length ALK receptor in thyroid cancer should be carefully re-evaluated." (PMID 28030793, 2017). "We aimed to investigate the prevalence of TERT promoter and ALK mutations in thyroid cancer patients with a high prevalence of the BRAF V600E mutation and their potential contribution for the risk stratification of these patients." (PMID 26857243, 2016). "ALK gene rearrangements are mutually exclusive with all other known thyroid cancer driver mutations and have been reported in up to 2.2 % of PTCs, 4 % of poorly differentiated carcinomas, and 4 % of anaplastic carcinomas." (PMID 26857243, 2016). "Our study demonstrated that Korean patients have a higher BRAF V600E prevalence and lower prevalence of the TERT promoter mutation and ALK rearrangement in thyroid cancers than do Western patients." (PMID 26857243, 2016). "In particular, anaplastic lymphoma kinase (ALK) gene fusions have been associated with aggressive thyroid cancers, whereby rearrangements with ALK result in tumorigenic activity." (PMID 25276134, 2014). "ALK gene fusion-associated thyroid carcinomas can show subtle cytologic nuclear features resembling RAS-like tumors and present with a myriad of architectural patterns such as classic, classic with a predominant microfollicular growth, infiltrative follicular, and solid-trabecular." (PMID 40111709, 2025). "ALK mutations and fusions are uncommon events in thyroid cancer." (PMID 31583077, 2018). "In contrast to the single report of activating ALK mutations (ALK-L1198F and ALK-G1201E) in the full length receptor, a number of articles have reported ALK fusion genes in thyroid cancer, where they appear to represent a small fraction of papillary thyroid carcinoma (PTC)." (PMID 28030793, 2017). "However, little is known about the impact of TERT promoter mutations and ALK rearrangement in thyroid cancer patients with a high prevalence of BRAF mutations." (PMID 26857243, 2016). "The recent discovery of anaplastic lymphoma kinase (ALK) gene mutations in thyroid cancer may rationalize clinical evaluation of ALK inhibitors in this setting." (PMID 22654559, 2011). "The proliferation of thyroid cancer cells induced by ALK fusions in vitro and in nude mice was blocked by crizotinib and TAE684 (ALK inhibitors), which indicated ALK fusions as a potential therapeutic target of thyroid carcinomas." (PMID 37622214, 2024). "The frequency of ALK fusion genes in thyroid carcinoma ranges from approximately 1 to 4%, with a slightly higher frequency of 6% in pediatric PTC cases." (PMID 38472412, 2024). "ALK fusions are still more rare in well differentiated thyroid cancers (<1% of PTC) but are identified more frequently in PDTC." (PMID 36909304, 2023). "Genomic profiling of thyroid cancers has led to the discovery of ALK rearrangements in around 2% of PTCs, including a novel ALK fusion product,STRN-ALK, that is sensitive to available ALK inhibitors." (PMID 37434642, 2023).